BRAF (B-Raf proto-oncogene, serine/threonine kinase)
Diseases named in the same sentence as BRAF in open-access papers (continued):
Sharing a sentence is not in itself a finding about the gene and the disease.
melanoma (continued). "However, due to the potent re-activation of MAPK pathway in melanoma selective BRAF inhibitors are used in the treatment of patients with BRAF-mutant advanced melanoma." (PMID 33212834, 2020). "Moreover, though we observed increased PKA activation in BRAF/MEK inhibitor-resistant melanoma cells, the mechanism behind PKA activation and its impact on the resistance acquisition need to be further investigated." (PMID 33396632, 2020). "Moreover, we reported that NRP1 expression is markedly upregulated in BRAF-inhibitor-resistant melanoma cells; however, the mechanism triggering NRP1 activity was not elucidated." (PMID 32784465, 2020). "A recent report showed that translocation of the entire ERK signaling pathway to endoplasmic reticulum could drive therapy resistance in BRAF-mutant melanoma, indicating a therapeutic potential of simultaneous targeting of ER and BRAF in melanoma." (PMID 32531927, 2020). "However, the strength of our work encompasses the demonstration of the capability of RTIs to delay resistance to target therapy in BRAF-mutant melanoma cells in vitro." (PMID 32933538, 2020). "Furthermore, we show that miR-204-5p and miR-199b-5p are able to potentiate also the combination of a BRAF and a MEK inhibitor, which currently represent the gold standard of therapy for BRAF mutant melanoma patients." (PMID 32178301, 2020). "Indeed, HGF expression was correlated with innate resistance to BRAF inhibition, and increased HGF plasma levels predicted worse overall survival (OS) and progression-free survival (PFS) in BRAF-mutant melanoma patients." (PMID 33553157, 2020). "Additionally, data are sparse concerning optimal strategies for treatment sequencing in advanced melanoma, especially for BRAF‐mutant disease." (PMID 32871054, 2020). "In contrast, 24% of melanomas positive for BRAF mutations were the histological subtype ALM, which is not related to sun exposure." (PMID 32775409, 2020). "Mutations of BRAF, NRAS, and KIT genes have been correlated to the development of melanoma." (PMID 31274706, 2020). "High tumor expression of CD73 has also been observed in BRAF-mutant melanoma patients." (PMID 32160899, 2020). "All melanoma of unknown primary origin harbored a BRAF alteration (100%, 4/4 samples), whereas an alteration of BRAF gene was recorded in 40.4 % (38/94) of cutaneous melanomas, 28.6% (2/7) of acral melanomas and in 11.1% (1/9) of the mucosal melanomas." (PMID 36046072, 2020). "Combining an AMPK activator with BRAF inhibitor can be a good therapeutical option in melanoma." (PMID 32509589, 2020). "Recently, we reported that BRAF-mutated melanoma cells converge toward a non-quiescent “idling population state” upon long-term MAPKi treatment." (PMID 32923395, 2020). "In addition to T cells, an increased number of natural killer cells have been demonstrated in tumour infiltrates in a mouse model of BRAF-mutant melanoma after treatment with a BRAF inhibitor." (PMID 32645969, 2020). "In melanoma cells, the altered signaling pathways in SK-MEL-147 cells, which have an NRAS mutation and 501Mel cells, which have a BRAF mutation, could also be a reason for the differential response to BET inhibitors." (PMID 32151278, 2020). "Exposure of BRAF V600E driven melanoma cells to sublethal levels to the BRAF inhibitor vemurafenib or the DNA damaging agent cisplatin led to the development of a less differentiated, drug-tolerant state characterized by the enrichment of slow-cycling, long-term tumor-maintaining melanoma cells." (PMID 32046099, 2020). "The mainstream of chemotherapy for melanoma is BRAF inhibitors." (PMID 32169117, 2020).
melanoma (continued). "Taken together, these data indicate that the triple combination may be an effective therapy for treatment-refractory BRAF-driven melanomas." (PMID 33122628, 2020). "BRAF inhibition in fact induces the formation (by melanoma cells) of a fibronectin-derived protective niche that activates signaling from α5β1 integrin/PI3K/AKT leading to an increase in the expression of the pro-survival myeloid cell leukemia 1 (MCL1) protein that mediates therapeutic escape." (PMID 32466585, 2020). "Resistance to targeted BRAF inhibitors is widely existed in melanoma." (PMID 33614479, 2020). "Treatment with BRAF inhibitors will only inhibit the mutant monomer in BRAF mutant melanoma cells." (PMID 32092958, 2020). "Increasing klotho levels may improve the therapeutic effect of BRAF inhibitors by targeting Wnt signaling in melanoma patients of advanced age." (PMID 33373316, 2020). "The FDA has approved mutant BRAF inhibitors for melanoma therapy." (PMID 32863956, 2020). "Importantly, the signature of genes belonging to this network showed a prognostic potential for BRAF-mutant melanoma patients based on The Cancer Genome Atlas (TCGA) data." (PMID 33202944, 2020). "In addition there was differential in vitro elimination of both BRAF inhibitor sensitive and resistant melanoma cells by B7-H3- or CSPG4-specific CAR T cells." (PMID 32894202, 2020). "As NF1 deficiency mediated escape from BRAF-driven OIS and BRAF inhibitor resistance in melanoma, which could be combatted with MEK inhibitors, we hypothesize NF1 loss may be a key targetable mechanism of resistance to PI3K/AKT/mTORC1 inhibitors." (PMID 31285545, 2020). "Since 2011, much excitement has been generated in the melanoma field, with the development and US Food and Drug Administration approval of novel targeted therapies (e. g., small molecule BRAF and MEK inhibitors) and immune checkpoint inhibitor therapies (e. g., Anti-CTLA4 and Anti-PDL-1 antibodies)." (PMID 33378390, 2020). "BRAF V600E mutation causes aberrant MAPK signaling and drives 40–50% of melanomas, 10% of colorectal cancers,1–2% of lung adenocarcinomas, 50% of the well differentiated thyroid carcinomas and the vast majority of hairy cell leukemia cases following the oncogene addiction disease model." (PMID 32131760, 2020). "Here we sought to determine whether oncosuppressor miRNAs carrying LNPs could be able to potentiate the growth inhibitory effects of MAPKi in BRAF-mutant melanoma cells." (PMID 32178301, 2020). "Subsequently, BRAF inhibitors were developed for the treatment of patients with melanoma." (PMID 32260561, 2020). "In addition, BRAF mutant melanoma cell lines, PAK1 has been shown to phosphorylate the pro-apoptotic protein Bad, preventing its association with Bcl-2 and the subsequent release of cytochrome C from mitochondria." (PMID 32309283, 2020). "These four compounds may provide a basis for enhanced immune recognition and design of novel therapeutic approaches for patients with BRAF mutant melanoma resistant to ACT due to antigen downregulation." (PMID 32231230, 2020). "In this study, we analyzed the cutaneous melanoma TCGA transcriptomic and proteomic database for differential expression of apoptosis molecules between melanomas with or without BRAF hotspot mutations." (PMID 32764384, 2020). "The same study shows that NRAS+ nor BRAF+ was associated with overall melanoma-specific survival, but the risk of death was significantly more reduced for higher-risk NRAS+ or BRAF+ (T2 or higher stage)." (PMID 32637031, 2020). "Since multidrug therapeutic regimens have shown a reduced risk of non-specific adverse effects, the strong efficacy of NRP1/Gal-1 combined targeting offers a promising perspective for regaining therapeutic efficacy for BRAF inhibitors in melanomas that have developed drug-resistance." (PMID 32784465, 2020).
melanoma (continued). "A possible explanation is that melanomas without BRAF mutations require accumulation of high UV doses over time, further supported by the difference in anatomic site of primary tumor." (PMID 32726988, 2020). "However and in contrast, our recent study showed that Y-27632 actually promotes the growth of human BRAF-mutant melanoma cells." (PMID 32843583, 2020). "Although BRAF (V600E) exists only in ~ 7% of all cancers, it is highly prevalent in some tissue-specific cancers such as melanoma (50~60%), thyroid cancer (40~50%), and histiocytosis (~50%), albeit the underlying molecular mechanism(s) remains unknown." (PMID 32807225, 2020). "Similarly, mTOR inhibitor everolimus is shown to selectively target BRAF-mutant melanoma in acidic condition." (PMID 33262326, 2020). "The P29S mutation in the RAC1 gene is found in 3.3% of melanomas, but in as many as about 20% of patients not responding to treatment with BRAF inhibitors." (PMID 32605090, 2020). "Considering that our data showing BIM knockout or knockdown results in decreased melanoma sensitivity to this combination, we speculate that higher BIM expression may be a contributing factor for a better response in BRAF-WT melanoma." (PMID 32764384, 2020). "In addition, circulating VEGF has been indicated as a predictive biomarker for a response of melanoma patients to BRAF/MEK inhibitors, and for monitoring the onset of drug resistance." (PMID 32466509, 2020). "Therefore, mitochondria and OXPHOS represent metabolic vulnerabilities to exploit for the design of new and more effective therapeutic strategies targeting both PGC1-α-positive melanomas and BRAF mutant melanomas." (PMID 32528879, 2020). "If mutations in a given gene or pathway are seen in a large enough fraction of a given tumor histology, it brings attention to that gene/pathway as having a possible critical role in the disease under study—with BCR-ABL in CML and BRAF in melanoma the two best examples." (PMID 33148256, 2020). "Since Gal‐1 favors the expansion of these cell populations, increased infiltrates of these cells in BRAF inhibitor‐treated melanomas might be driven, at least partially, by Gal‐1 overexpression." (PMID 32330348, 2020). "Unlike non-small cell lung cancer, BRAF mutations that do not affect codon 600 (non-600) are particularly infrequent in melanoma." (PMID 32825562, 2020). "Based on these findings, it was concluded that PI3K-Akt-CREB-AEBP1-NF-κB pathway may be presented as a novel pathway whose activation promotes acquired resistance to BRAF inhibitors in melanoma." (PMID 32565808, 2020). "Upregulation of autophagy is known to be an adaptive response in BRAF-inhibitor resistant melanoma." (PMID 32226547, 2020). "Most melanoma patients harbor mutations in the mitogen-activated protein kinase (MAPK) pathway (BRAF-MEK-ERK) (BRAFV600E being the most common) and therefore, benefit from targeted therapies against MAPK pathway (BRAF and MEK inhibitors)." (PMID 32391428, 2020). "Also, the recent work on the resistance mechanisms in melanoma patients treated with BRAF or MEK inhibitor therapy revealed new therapeutic strategies." (PMID 32825510, 2020). "Finally, the combined treatment with a Gal-1 inhibitor and a NRP1 blocking drug enabled resistant melanoma cell resensitization to BRAF-targeted therapy." (PMID 32784465, 2020). "Furthermore, the BRAFi/MEKi/2 + 5BETi schedule delayed tumour growth in a BRAF-mutant melanoma patient-derived xenograft (PDX) model." (PMID 31932756, 2020). "In BRAF-mutant melanoma, BIM contributes to apoptosis induced by BRAF or MEK inhibitor treatment." (PMID 32344828, 2020). "CEACAM1 is downregulated prior to resistance development, suggesting that it may be a future target for the treatment of BRAF inhibitor-resistant melanoma." (PMID 33003483, 2020).
melanoma (continued). "We proposed to standardize a liquid biopsy platform to identify hotspot mutations in BRAF, NRAS and TERT in plasma samples from advanced melanoma patients and investigate whether it was associated to clinical outcome." (PMID 33122747, 2020). "Furthermore, patients with BRAF-mutant melanoma now have a new treatment option: Encorafenib (a new generation BRAFi) with binimetinib (a new generation MEKi)." (PMID 32013263, 2020). "Response to BRAF inhibitors (BRAFi) may be determined by intratumoral immune activation within melanoma metastases." (PMID 32528881, 2020). "There are reports of higher incidences of discontinuing ICI treatment because of significant hepatotoxicity in patients receiving sunitinib or pazopanib with nivolumab for treatment of renal cell carcinoma (RCC) and using ipilimumab with BRAF inhibitors for treatment of melanoma." (PMID 32507925, 2020). "Moreover, in melanoma cell lines that are resistant to BRAF/MEK inhibitors, this miRNA expression was reported as low." (PMID 32185171, 2020). "Previous studies have shown that BRAF inhibition in melanoma cell lines resulted in a decreased secretion of immunosuppressive factors like IL-10, VEGF, and IL-6 and enhanced expression of melanocyte differentiation antigens (MDA) to improve recognition by MDA-specific T cells." (PMID 31541179, 2020). "The treatment combination of trametinib, a pyrido-pyrimidine derivative, and dabrafenib, a BRAF inhibitor, is currently under evaluation in phase 2 clinical trials for treating patients with BRAF mutant resectable stage III melanoma (ClinicalTrials.gov identifier: NCT02858921)." (PMID 32456226, 2020). "Therefore, a variety of BRAF (V600E) inhibitors can be clinically used as promising drugs in the treatment of melanoma." (PMID 31733641, 2020). "Here, we report a pilot study of CTCs purified from a homogeneous group of stage IIIC melanoma patients with locoregional, BRAF wild-type metastases located exclusively to pelvic region, who were not eligible for immune checkpoint inhibitor therapy and were submitted for melphalan HPP therapy." (PMID 32204733, 2020). "Similarly, melanoma patients who discontinue BRAF (B-Raf Proto-Oncogene)-directed therapy due to progression or other causes can benefit from retreatment at a later stage." (PMID 32365663, 2020). "Thus, these compounds confirmed in a human BRAF mutant melanoma cell model and are promising candidates to be used to potentiate T cell recognition in melanoma patients." (PMID 32231230, 2020). "Recently, it has been reported that lack of Cdkn2a in V600E BRAF mutated melanocytes in rodents is associated with rare progression to melanoma." (PMID 32556513, 2020). "In this respect, VEGF-dependent neuropilin signaling has been reported to play a relevant role in cancer; however, we have previously shown that VEGF is unlikely to be implicated in establishing NRP1-dependent melanoma resistance to BRAF inhibitors." (PMID 32784465, 2020). "Furthermore, constitutively activated BRAF(V600E) in melanoma tumor cells has been shown to initiate and sustain IL-1α/β-dependent T-cell suppression in a murine model." (PMID 32604720, 2020). "Understanding how the cancer cells evade BRAF inhibition may promote the development of novel therapeutic strategies in BRAF-mutant melanoma patients and other BRAF-dependent tumors." (PMID 32413516, 2020). "Consequently, dual MAPK inhibition with the combination of a BRAF inhibitor plus an MEK inhibitor is a standard-of-care approach for patients with unresectable or metastatic BRAF-mutant melanoma." (PMID 32645969, 2020). "IRS-1 remained significantly higher in NRAS mutant vs BRAF mutant melanomas at the protein level." (PMID 33082316, 2020). "BRAF mutations are observed in about 52% of malignant melanoma cases, but EWSR1 rearrangement has not been identified in malignant melanoma." (PMID 32316685, 2020).
melanoma (continued). "For instance, BRAF V600E driver mutations are discerned at twice the frequency in benign nevi, which do not transform to melanoma, than in melanoma itself." (PMID 32066498, 2020). "Removing this protective mechanism through the combined use of MEK/ERK inhibitors and autophagy inhibitors may be therapeutically beneficial in patients with PDAC, NRAS-driven melanoma, and BRAF-mutant colorectal cancer." (PMID 31355143, 2019). "Finally, it was reported that ectopic expression of RAC1P29S in BRAF mutant melanoma cells generates resistance to BRAF inhibition and that three patients with the mutation responded particularly poorly to a BRAF inhibitor." (PMID 31257073, 2019). "Therefore, we were interested in pursuing drugs predicted in combination with BRAF inhibitors for prospective validation for BRAF-mutant melanoma." (PMID 30820351, 2019). "However, most genes have been largely constrained to organ-specific analysis (e.g. estrogen receptor /HER2 for breast cancer, KRAS for colorectal cancer, BRAF for melanoma, etc.)." (PMID 30847023, 2019). "A recent study conducted on BRAF-mutant melanoma xenografts demonstrated that the combination of the BRAFi PLX4720 and bevacizumab was more effective than each single agent in inhibiting tumor growth and metastasis and also delayed the onset of acquired resistance." (PMID 31227006, 2019). "In addition to conventional therapy, melanoma treatment is currently based on targeting the BRAF/MEK/ERK signaling pathway and immune checkpoints." (PMID 30674989, 2019). "Targeted sequencing of individual genes to guide therapy has become the standard of care for several different cancer types, including colorectal cancer (KRAS, BRAF, and NRAS), lung cancer (KRAS and EGFR), melanoma (BRAF), GI stromal tumor (KIT), and gliomas (IDH1 and IDH2)." (PMID 32914008, 2019). "Our findings also could implicate that EGFR + BRAF + MEK combination therapy might improve efficacy of targeted therapy also in melanoma patients." (PMID 31514305, 2019). "The clinical efficacy of NIVO in combination with IPI in advanced melanoma patients, with and without the BRAF V600 mutation, has been demonstrated in the CheckMate 067 study." (PMID 31312536, 2019). "Finally, we presented prospective validation of the drug combination of vemurafenib (BRAF inhibitor) and tretinoin (all-trans retinoic acid (ATRA)) predicted by our method for BRAF-mutant melanoma." (PMID 30820351, 2019). "However, MAF of driver mutation was found to be significantly increased only in metastases of BRAF mutant melanomas." (PMID 31391014, 2019). "At the cellular level, we observed that the exposure of BRAF-mutant melanoma cells to 1 resulted in a pronounced down-modulation of KIT, which was paralleled by the shutdown of the RAS/RAF/MAPK and PI3K/AKT signaling pathways, both at the transcriptomic and post-translational levels." (PMID 31635389, 2019). "Furthermore, KIT mRNA expression was significantly higher in patients showing clinical benefit from the combined therapy, emphasizing the tumor-suppressor role of KIT already described within the context of BRAF-mutant melanoma." (PMID 31426590, 2019). "Whereas PD-L1 protein level were significantly increased in BRAF V600E mut melanoma cell lines resistant to BRAF inhibition, this effect was decreased both after using small interfering RNA (siRNA) mediated knockdown of ERK1/2, and after pharmacologic inhibition of MEK." (PMID 35582595, 2019). "A similar response was observed in seven additional melanoma cell lines regardless of the presence or absence of BRAF or NRAS oncogenic mutations." (PMID 31040916, 2019). "In addition, induced expression of NAMPT was able to render melanoma cells resistant to BRAF inhibitors while BRAF inhibition in sensitive cells resulted in transcriptional downregulation of NAMPT." (PMID 32010616, 2019).